CD4 (CD4 molecule)
Diseases named in the same sentence as CD4 in open-access papers (continued):
Sharing a sentence is not in itself a finding about the gene and the disease.
tumor (continued). "However, it is known that the CD4+ and CD25+ markers contain populations of Tregs and effector T-cells 6 and Foxp3+ is not restricted to Tregs and may be also activated in other cell types, such as effector T-cells and tumor cells." (PMID 38781760, 2024). "Notably, the depletion of either CD4+ or CD8+ T cells significantly compromised the efficacy of anti-PD-1 therapy, highlighting the critical role of SFB-induced CD4+ T cells in facilitating the maturation and function of cytotoxic CD8+ T cells within the tumor." (PMID 39185202, 2024). "However, the observed role of CD4 T cells in tumor control cannot be ruled out given the capacity of TCPTP inhibition to dysregulate the formation and maintenance of Tregs, while promoting Th1 and Th17 differentiation of CD4 T cells, both known to be beneficial for tumor clearance." (PMID 38707187, 2024). "Interestingly, a study published by the other group showed that the depletion of CD8 cells significantly reduced the mouse survival when treated with doxorubicin, while CD4 depletion did not, which demonstrated that the reduced tumor growth is CD8+ T cell dependent." (PMID 39247806, 2024). "Similarly, CD4+ TH17 cells, which were overrepresented in the non-responder groups, exhibit context-dependent roles in tumor immunity and may be associated with both unfavorable and favorable outcomes." (PMID 39514276, 2024). "Notably, an obvious decrease in the proportion of regulatory T cells (CD3+CD4+Foxp3+, Tregs) was also seen in the PEG‐CuP‐COF@∆St + US group, demonstrating that PEG‐CuP‐COF@∆St + US‐mediated pyroptosis effectively reduced immunosuppression and remodeled tumor microenvironment." (PMID 39494618, 2024). "As helper CD4 T cells play a crucial role in enhancing the proliferation of CTL clones and guiding their transformation into effector and memory cells, incorporating Th epitopes may direct the vaccine-induced anti-tumor response towards sustainable and comprehensive regulation." (PMID 38675774, 2024). "Increased TGFβ activity may suppress antitumor response through inhibiting CD4 + T helper cell function (TH1 and TH2), decreasing differentiation and function of cytotoxic T cells, promoting pro-tumor TH17 response, and recruiting immune suppressive myeloid cells into the tumor microenvironment." (PMID 37858184, 2023). "Therefore, we assessed the accumulation of CD8+, CD4+ T cells, and NK cells and the concentrations of their effector molecules (IFN-γ and granzyme B) in the bronchioalveolar lavage fluid (BALF) of previously immunized mice that were subsequently challenged with 4T1 tumor cells." (PMID 36839766, 2023). "However, analysis of immune cell subsets cultured with anti–PD-1–resistant tumor cells in the presence of a pan-LPAR inhibitor revealed that some immunosuppressive populations are affected by LPA, as pan-LPAR blockade increased suppressive CD4+ Tregs and decreased effector CD4+ cells." (PMID 37655662, 2023). "Clearance of tumor cell debris may further deprive macrophages and other antigen presenting cells of tumor antigenic peptides which would otherwise be presented to T cells, either through Major Histocompatibility Complex II (MHCII) to CD4+ T cells, or through cross-presentation to CD8+ T cells." (PMID 37936688, 2023). "From single cell RNA-seq, Zander and colleagues show that the formation of effector CD8+ T cells is critically dependent on CD4+ T cell under the function of IL-21 and the pathway could be used therapeutically to enhance the killer function of CD8+ T cells infiltrating into the tumor." (PMID 38082437, 2023). "In addition to STING activation, the present study found that S100 monotherapy could upregulate the expression of Tim-3 in cDC2, subsequently diminishing the CD4+ T cell-mediated anti-tumor immunity; therefore, this negative impact could be relieved by αTim-3." (PMID 37771774, 2023).
tumor (continued). "Instead, considering FOXP3+ cells, which include both CD4+/FOXP3+ cells (Treg) and CD8+/FOXP3+ cells (activated CD8 T cells), the evidence is discordant, maybe because this biomarker is expressed by immune cells involved both in tumor suppression and in tumor progression." (PMID 36765724, 2023). "However, the role of CD4+ T cells in the anti-tumor response has not been elucidated." (PMID 38328405, 2023). "While transfer of 3 × 106 cells expressing TCR 1 was no longer sufficient for complete tumor rejection against the less-immunogenic parental cell line, tumor growth was still significantly delayed compared to untreated mice or mice receiving 3 × 106 polyclonal activated CD4+ T cells." (PMID 37400675, 2023). "However, some studies reported this expression just on tumor-infiltrating CD4+ T-cells, and infrequently on tumor cells, or could not find IL-25 in the T-cells isolated from the tumoral and adjacent tissues of the patients with different molecular subtypes." (PMID 37835465, 2023). "Similarly, transcriptomic profiling of tumor-infiltrating neoantigen-reactive T cells of gastrointestinal cancer patients delineated an exhausted phenotype in the majority of CD8+ and CD4+ neoantigen-reactive TILs and showed that GPR56 was up-regulated significantly in CD4+ neoantigen-reactive TILs." (PMID 36982575, 2023). "Thus, the potential increase in CD39−/+CD73+CD4+ cells in HPV− HNSCC patients may represent a heightened Th17 or Th1.17 inflammatory state compared to HPV+ HNSCC patients, possibly in response to different tumour aetiology and antigen expression." (PMID 37628721, 2023). "Furthermore, the association between cytotoxic CD4 T cells and response to anti-PDL1 therapy only held in patients with immune-inflamed tumors, not in immune excluded or desert tumors where the CD4 T cells would not be in contact with the tumor cells." (PMID 37654482, 2023). "Moreover, other immune cells (CD3+/CD4+ helper T cells, CD3+/CD1d+ NKT cells, CD3−/CD56+ NK cells, CD3+/TCRγδ+ T cells, and CD3−/CD11c+/HLA-DR+ dendritic cells) may effectively cooperate to kill tumor cells." (PMID 37100864, 2023). "Furthermore, CD4+ T cells can eradicate the tumor cells even in the absence of CD8+ T cells." (PMID 39086686, 2023). "However, in a murine colorectal model, targeting galectin-1 did not lower the frequency of CD4+CD25+ Tregs in the tumor, spleen as well as tumor-draining lymph nodes, whereas the proportion and immunosuppressive properties of CD8+CD122+PD-1+ Tregs were reduced." (PMID 37047471, 2023). "Additionally, significant Breg expression in patients seems to be closely linked to increased Treg cell production either peripherally or in the tumor microenvironment (TME), enhancing the conversion of nonactivated CD4+ cells into Tregs, with a decline in cytotoxic T-cell response in tumor tissue." (PMID 37068081, 2023). "Moreover, using the anti-CD8 antibody depleted of CD8+ T cells in animals with LR-DPVB weakened tumor regression, while the anti-CD4 antibody could not." (PMID 38001101, 2023). "Furthermore, CIBERSORT analysis demonstrated that ICD score has positive correlations with the proportions of T cells CD4 memory activated, T cells gamma delta, and negative correlations with the proportions of macrophages M0 among the 22 tumor-infiltrating lymphocyte types (p < 0.05)." (PMID 37990304, 2023). "Blocking of either CD8+ T or CD4+ T cells resulted in the partial inhibition of tumor growth, while the depletion of NK cells or macrophages did not affect tumor growth inhibition, indicating that CD8+ and CD4+ T both played important roles in anti-tumor effects." (PMID 37771774, 2023). "Therefore, the role of CD4+ T cells in tumor therapy has not received much attention." (PMID 37649123, 2023).
tumor (continued). "In vivo experiment showed that depletion of CD4(+) T lymphocytes lead to inhibition of antitumor activity and decreased antibodies against MMP-2, indicating that contribution of immune response against MMP-2 might be potential novel tumor methods for cancer therapy." (PMID 37766868, 2023). "Additionally, significant Breg expression in patients seems to be closely linked to increased Treg cell production either peripherally or in the TME, postulating their role in the conversion of nonactivated CD4+ cells into Tregs, with a decline in cytotoxic T-cell response in tumor tissue." (PMID 37068081, 2023). "Furthermore, IL-2, IL-12, IFN-γ and TNF-α have been reported to stimulate CD4+ Th1 differentiation and accelerate Th1-mediated antitumor responses; In addition, these cytokines stimulate CD8+ cytotoxic T lymphocytes (CTLs), the most important effector cells that recognize and eliminate tumor cells." (PMID 37048096, 2023). "Unlike CD8+ TILs, CD4+ TILs might contribute to anti-tumor immunity via cytokines." (PMID 36693070, 2023). "Importantly, accurate analysis of the tumor tissue demonstrates that tumor rejection correlates with increased infiltration of T lymphocytes, particularly CD4+ and CD8+ T cells, but not B cells or natural killer (NK) cells, and with profound subversion of the tumor microenvironment." (PMID 36993983, 2023). "Higher tumor cell death might be directly due to loss of CD70 co-stimulation in co-cultured CD4+ naïve T cells and Tregs induced by CD70-NC C666 cells rather than CD4+ and CD8+ T cells in the co-culture system." (PMID 37024479, 2023). "To determine whether the presence of relatively high numbers of proliferating and activating CD8 and CD4 T cells has an effect on the progression of KP2-OXPARPi tumors, we depleted CD4 and CD8 T cells using CD4 and CD8 depleting antibodies to KP2-OXPARPi tumor-bearing mice." (PMID 37179276, 2023). "Notably, the treatment group had similar ratios of CD4+/CD45+ cells before tumor rechallenge; however, the treatment group had a significantly higher ratio of CD4+/CD45+ cells (46.9% ± 1.3% vs. 33.3% ± 0.6%) after tumor rechallenge, compared with the control group." (PMID 37345658, 2023). "Interestingly, selective analysis of the tumor-infiltrating T cells (of CD3+ cells instead of total cells) indicated that the ICOS/PD-1 combination therapy increased the percentage of cytotoxic CD8+ T cells and, at the same time, reduced the percentage of CD4+ effector cells." (PMID 36266600, 2023). "In addition, the number of tumor‐infiltrating CD4+ T‐cells showed no significant variation." (PMID 37565362, 2023). "In addition, both CD4+ and CD8+ T-lymphocytes were increased significantly in the combination group compared with the control group, suggesting that the immunomodulatory function of Rh2 may play a role in therapeutic efficacy in CT26/luc tumor-bearing mice." (PMID 37764996, 2023). "A plausible explanation would seem to be that Treg CD4 + T cells may play a negative role in regulating immune response by secreting inhibitory cytokines in various immune cell subsets, which may lead to the immune escape of tumor cells." (PMID 36982415, 2023). "Notably, tumor control was abrogated by depletion of CD4 but not CD8 T cells." (PMID 37185301, 2023). "However, the authors speculated that this phenomenon was likely due to a homeostatic defect rather than to a CXCR3-dependent effect, although no changes in the numbers of tumor-infiltrating CD4+ and CD8+ cells in the tumor was observed." (PMID 38104126, 2023). "Besides, we also observed a significant increase of tumor-infiltrating tissue-resident memory T cells and effector memory T cells in both CD4+ and CD8+ T cell subsets from combination-treated mice, revealing memory CD8+ /CD4+ T cells were activated after combination therapy." (PMID 37771774, 2023).
tumor (continued). "Therefore, caution should be exercised in fully characterizing the tumor (e.g., CD4 or CD8; does the tumor itself bear KLRK1, or is it expressed by the infiltrating T cells) to ascertain whether KLRK1 both as a biomarker and a potential treatment target is beneficial or detrimental." (PMID 38026637, 2023). "By contrast, although significant differences in PD1 expression on CD4+ and CD8+ T cells and their subpopulations were not identified, a strong positive correlation between PD1 expression on circulating and tumor-infiltrating CD8+ cytotoxic T cells could be observed." (PMID 36497232, 2022). "Interestingly, positive correlations among CLST, liver-resident CD4+ T naïve-like cells (CD4+TLR-NL), acquisition of a TH17 polarization state (CD4+TLR-NL), CD4+TEM-TH1/TH17, and immune checkpoints (ICs) indicated their cross-talk in the tumor tissue of HBV-HCC." (PMID 36569318, 2022). "We propose that measuring the availability of potential tumor antigens and the infiltration of CD4+ and CD8+ T cells with cytotoxic phenotypes may aid in resolving the contradictory findings of these studies and provide a more complete picture of the tumor immune microenvironment." (PMID 35831288, 2022). "Seeing that there were TIL cultures with a greater proportion of CD4+FOXP3+ T-cells, it is unclear whether the in vitro expansion environment induced FOXP3 expression or there were already greater proportions of CD4+FOXP3+ T-cells within the tumour specimens prior to expansion." (PMID 35158816, 2022). "In addition, some patients had tumor infiltrating B cells (TIL-Bs) that could activate CD4+ tumor infiltrating lymphocytes (TILs) without exogenous antigen." (PMID 36159874, 2022). "Interestingly we found that treatment with Ca alone resulted in a higher frequency of CD4+ PD-1+ T cells in the tumor (V=80.3 ± 2.2, Ca =89.7 ± 1.3; p=0.006), but not the spleen, and that there was a higher frequency of PD-1+ T cells in the TILs relative to the spleen, regardless of treatment." (PMID 36419897, 2022). "The results showed that the sum of the CD8+ and CD4+ percentages was related to the postoperative survival of patients, which may be related to the immune effect of CD8+; the higher the CD8+ CD4+ value is, the stronger the immune effect of the tumor, and the higher the SR." (PMID 36124030, 2022). "To identify tumor-related immune cells and whether specific immune cell types were differentially enriched in either ERG + or ERG− samples, we analyzed the T-cell population and identified CD4 and CD8 T-cells, regulatory T-cells (Treg), and NK cells based on differentially expressed genes." (PMID 35013146, 2022). "Furthermore, the CD8+ T-cells (CD45+, TCRβ+/CD8+, CD4−) expressed greater amounts of granzyme B molecules in the CpG group and CpG/aOX40 group, compared to the isotype treated tumors, suggesting that the specific treatments increased CD8 T-cell functionality and ability to initiate tumor killing." (PMID 35760778, 2022). "The CD4:CD8 ratio in oropharyngeal cancer was 3-fold higher than that in cervical cancer, emphasising that anatomical location is an important factor for immunogenicity of a tumour and in consequence may—together with exposure to carcinogenic factors—shape the evolutionary trajectory of tumours." (PMID 36476325, 2022). "Finally, we recently reported that CD4 T cells specific for the cancer-testis antigen NY-ESO-1, either naturally occurring or induced by long synthetic peptide immunization in combination with CpG, were able to efficiently kill tumour cells in an MHC class II-restricted manner." (PMID 35572552, 2022). "Additionally, the results of immune infiltration analysis showed that the expression of SLC25A11 was positively correlated with the recruitment of immune cells, such as CD8 + T, CD4 + T, and DC, which alludes that SLC25A11 may also play a role in anti-tumor immunity." (PMID 36514121, 2022).
tumor (continued). "If extrapolated beyond CD4+ T cells, our results on IL-10 signaling supporting the long-term maintenance of immunological memory may help explain recent data showing that IL-10R signaling favors the maintenance of a population of CD8+ T cells that promote tumor control in oncology models." (PMID 35230978, 2022). "In addition, our analysis of tumor cell infiltrates revealed neutrophils’ role in facilitating complex remodeling of the lymphoid and myeloid cell landscape, including more than 6-fold in CD8+ and CD4+ Teffs and more than 3-fold in cDC2 i.t. sequestration in 7HP349-treated mice." (PMID 35552271, 2022). "Differences in chemokine receptor expression, tissue specificity, or activation requirements between CD4+ vs. CD8+ MAIT cells remain open questions and may, at least in part, explain the differences in the frequencies of MAIT cell subsets in the circulation and tumor microenvironment." (PMID 35028137, 2022). "The results showed significantly reduced numbers of B cells, CD4+ T cells, CD8+ T cells, neutrophils, DCs, NK cells, and Th1 cells in myCAF+ tumors, indicating that myCAFs might act as a physical barrier to prevent the infiltration of pro‐immunity cells into tumor areas." (PMID 35986392, 2022). "We observed positive correlations between the hTIL scores and percentages of total T, CD4+ T, and CD8+ T, but negative correlations between the hTIL scores and NK and NKT, showing that hTIL was associated with the degree of leukocyte infiltration in tumor tissue and leukocyte composition." (PMID 35577913, 2022). "Interestingly, the same study demonstrated that a significant percentage of CD8+ and CD4+ T cells in the tumor carried T-cell receptors recognizing TAAs not included in the vaccine, apparently the result of RT-enhanced TAA expression by the irradiated tumor cells." (PMID 35681654, 2022). "We first tested whether the receptors predicted by NicheNet were present as proteins, and found that IL1R1 was expressed specifically by tumour-infiltrating Treg cells, but not by tumour-infiltrating CD4+ T cells or CD8+ T cells, nor by T cells in the peripheral blood." (PMID 35545675, 2022). "Interestingly, the treatment of mouse syngeneic tumor models with EZH2 inhibitors resulted in the accumulation of CD11b+Gr1+ cells in the tumor tissue, an increase in M1 macrophages with the consequent decrease in M2 macrophages, as well as a reduction in IFN-γ-producing CD8+ and CD4+ T-cells." (PMID 36135315, 2022). "Furthermore, the percentages of CD4+ and CD8+ T cells were induced by the combination treatment in tumor tissues (p< 0.05), and the combined therapy increased the proportion of CD4+ T cells in the peripheral blood of mice, without affecting CD8+ T cells (p< 0.05)." (PMID 35992834, 2022). "Besides, the strong association between the expression of STAT and infiltration of multiple types of immune cells in CRC, including B cells, CD8+ T cells, CD4+ T cells, macrophages, neutrophils, and dendritic cells, demonstrates that STATs may play a role in the regulation of CRC tumor immunity." (PMID 36061181, 2022). "Finally, we isolated the CD15+ cells and CD4/CD8pos T cells at 24 h from APCCs and analyzed the expression of key immune‐suppressive genes of MDSCs (ARG1, NCF1, NCF4, CYBB) which mediate MDSC arginase 1 secretion and NO generation to inhibit T cells within the tumor TME." (PMID 35611994, 2022). "When flow cytometry and RT-qPCR analyses were conducted for immune cells isolated from the tumor tissues, we found that erastin by itself did not change the number of activated immune cells, including macrophages, dendritic cells, myeloid-derived suppressor cells (MDSCs), and CD4+ and CD8+ T cells." (PMID 35740445, 2022).